GLI2 (GLI family zinc finger 2)
Diseases named in the same sentence as GLI2 in open-access papers (continued):
Sharing a sentence is not in itself a finding about the gene and the disease.
holoprosencephaly (31 papers, 2009 to 2025). Holoprosencephaly (HPE) is a complex brain malformation resulting from incomplete cleavage of the prosencephalon, occurring between the 18th and 28th day of gestation, and affecting both the forebrain and face, which results in neurological manifestations and facial anomalies of variable severity. "These holoprosencephaly features were also found in human loss-of-function GLI2 mutations, but less severe compared to SHH mutations, which is reflected in the predictions of our neural tube closure model." (PMID 40034255, 2025). "Talking of GLI2, it can be considered a key effector of the sonic hedgehog (SHH) signaling pathway; heterozygous mutations in GLI2 are associated with a broad spectrum of phenotypes ranging from holoprosencephaly to CPHD." (PMID 40868191, 2025). "Pathogenetic variants of the GLI2 gene are associated with an autosomal dominant form of holoprosencephaly (HOLOPROSENCEPHALY 9; OMIM # 610829) with variable phenotypic expression and, in some cases, incomplete penetrance." (PMID 38790549, 2024). "GLI2 is a zinc-finger transcription factor involved in pituitary development, and GLI2 allelic variants can lead to holoprosencephaly, polydactyly, midfacial, and/or pituitary abnormalities." (PMID 37948564, 2023). "In mice, haploinsufficiency of Shh, or Gli2, which encodes a zinc finger transcription factor that acts as a mediator of hedgehog signaling, increases sensitivity to ethanol-induced holoprosencephaly." (PMID 35370658, 2022). "Mice with single-allele Gli2 mutation show an increased incidence of holoprosencephaly induced by vismodegib, a hedgehog pathway inhibitor." (PMID 35370658, 2022). "In humans, GLI2 pathogenic variants were associated with holoprosencephaly, oral cleft, polydactyly, and Culler-Jones Syndrome (OMIM 615849)." (PMID 35885957, 2022). "Exposure to alcohol at a critical time can cause holoprosencephaly in mice heterozygous for Shh and Gli2, while Shh+/− and Gli2+/− mice would otherwise have a normal phenotype." (PMID 34576017, 2021). "Heterozygous mutations of the GLI2 gene cause a variety of clinical phenotypes, ranging from asymptomatic cases to more severe clinical phenotypes including Culler-Jones syndrome and holoprosencephaly (HPE) or HPE-like syndrome." (PMID 31782289, 2020). "In humans, Gli2 mutations are mostly associated with median maxillary central incisor and hypopituitarism and rarely to classic holoprosencephaly." (PMID 33324176, 2020). "Mutations in GLI2 have been described as causative of a spectrum of clinical phenotypes, notably holoprosencephaly, hypopituitarism and postaxial polydactyl." (PMID 30629636, 2019). "Gli2 heterozygous mutations are associated with holoprosencephaly (HPE9; MIM: 610829) and Culler-Jones syndrome (MIM: 615849)." (PMID 30463396, 2018). "Single allele mutations in the Hh pathway genes Sonic Hedgehog (SHH) and GLI2 cause holoprosencephaly with extremely variable phenotypic penetrance in humans." (PMID 24586787, 2014). "Isolated holoprosencephaly caused by pathogenic GLI2 variants appears to be extremely rare." (PMID 41488893, 2025). "After evaluation at the Medical Genetics Department, molecular analysis showed a heterozygous variant of the GLI2 gene, for holoprosencephaly, which is classified as a class IV variant arising de novo, and which was absent in the DNA extracted from the blood of the parents." (PMID 38790549, 2024). "We also identified variants in the holoprosencephaly associated genes GLI2 and PTCH1." (PMID 38096238, 2023). "The GLI2 gene has been linked to Culler-Jones syndrome and Holoprosencephaly 9 (HPE9), and studies have reported that patients with pathogenic variants of the GLI2 gene demonstrate an autosomal dominant inheritance pattern, variable expressivity and incomplete penetrance." (PMID 37745857, 2023).
holoprosencephaly (continued). "The defects described and the Shh involvement in human holoprosencephaly (for review, refer Ming and Muenke, 1998) suggest that Gli2 mutations might be responsible for human diseases such as facial and forebrain midline structures congenital malformations." (PMID 35221935, 2022). "Moreover, variants of GLI2 have already been shown to play a pivotal role in the etiology of holoprosencephaly or holoprosencephaly‐like phenotype, of which one of the characteristic facial features are cleft lip/palate." (PMID 31386309, 2019). "However, only mutations of HOXD13 and FOXF1 have been reported in humans with VACTERL association, while SHH and GLI2 mutations are associated with holoprosencephaly." (PMID 28003020, 2016). "Loss-of-function mutations in the human GLI2 gene cause pituitary anomalies and holoprosencephaly." (PMID 27351100, 2016). "Mutations in GLi2 cause holoprosencephaly-like features with cleft lip and palate." (PMID 19884679, 2009). "GLI2 mutations are associated with holoprosencephaly (HPE) or HPE-like features with craniofacial anomalies, pituitary abnormalities and polydactyly." (PMID 33634051, 2020). "GLI2 is a zinc-finger transcription factor involved in the Sonic Hedgehog pathway, and GLI2 variants have been reported in holoprosencephaly (HPE) and/or holoprosencephaly-like (HPEL) phenotypes with pituitary anomalies and postaxial polydactyly." (PMID 33337535, 2021). "In a case report, a holoprosencephaly patient with bilateral cleft lip and palate was found to carry a submicroscopic heterozygous deletion of the GLI2 gene." (PMID 31386309, 2019). "GLI2, SHH, and PTCH1 represent key hedgehog pathway members, which are critical for craniofacial patterning, and variations in these genes have been associated with holoprosencephaly with CL/P." (PMID 37745857, 2023). "Holoprosencephaly occurs in 13q deletion syndrome (ZIC 2), 18p deletion syndrome (TGIF1), Smith Lemli Opitz (SLO, DHCR7), Hartsfield syndrome (FGFR1), Steinfeld (CDON or variants), Culler Jones (GLI2), hydrolethalus (HYLS1 and KIF7) and Pallister-Hall (GLI3)." (PMID 34576017, 2021). "GLI2 variants are not infrequently associated with combined pituitary hormone deficiency in isolation, without midline defects or other features of holoprosencephaly." (PMID 32060556, 2020). "Similarly, in humans with mutations in the GLI2 gene, pituitary anomalies are reported and a persistent BHC is an abnormality seen in holoprosencephaly." (PMID 23537390, 2013).
glioma (29 papers, 2010 to 2025). A benign or malignant brain and spinal cord tumor that arises from glial cells (astrocytes, oligodendrocytes, ependymal cells). "The sesquiterpene, buddlindeterpene B, shows affinity for the transcription factors GLI1 and GLI2 (glioma-associated oncogen, which are zinc finger proteins)." (PMID 34356473, 2021). "In the presence of Hh, the repressive action of PTCH1 on SMO is removed and the downstream pathway is mediated via the glioma-associated zinc transcription factors, Gli1 and Gli2, which translocate to the nucleus and activate Hh-target genes." (PMID 29423837, 2018). "Expression of Patched 1 (PTCH1), Smoothened (SMO), and glioma-associated zinc transcription factors (Gli1 and Gli2) were assessed in histological sections using immunohistochemistry and immunofluorescence (IF) techniques." (PMID 29423837, 2018). "Moreover, GLI2 expression has been strongly linked to many types of glial tumors, including astrocytomas, gangliogliomas, glioblastomas, ependymomas, and oligodendrogliomas, whereas GLI1 and 3 correlated preferably with oligodendrogliomas." (PMID 35409080, 2022). "The GLI2 gene belongs to the gli-kruppel family of transcription factors and was first identified through its amplification in human gliomas." (PMID 41488893, 2025). "Increasing ARL13B expression promotes the accumulation of both activated SMO and GLI2 in glioma cilia." (PMID 37830570, 2023). "COL1A1 is one of the downstream targets of the glioma-associated oncogenes (GLI1 and GLI2), is involved in collagen deposition, and is associated with PDAC aggression." (PMID 36038612, 2022). "The second region includes the GLI2 gene, which promotes cell proliferation and migration in glioma." (PMID 34827152, 2021). "Previous studies showed that GLI2 was up-regulated and facilitated cancer progression in multiple malignancies, such as glioma, colorectal cancer and bladder cancer." (PMID 34657624, 2021). "The target gene of Gli2 can mediate the Hedgehog signaling pathway to facilitate the occurrence of glioma." (PMID 35201446, 2021). "In this study, we identified ARHGEF16 as a target gene of GLI2 that interacts with cytoskeleton-associated protein 5 (CKAP5) to regulate glioma cell migration and proliferation, thus promoting glioma progression." (PMID 30305138, 2018). "In human glioma cells, miR-124 is a key downstream target gene of the Hh pathway, and inhibiting the Hh pathway suppresses cell growth via the Gli2/miR-124/AURKA pathway." (PMID 29899399, 2018). "Based on these results, we selected ARHGEF16 as a candidate gene regulated by GLI2 affecting cell proliferation and migration in glioma." (PMID 30305138, 2018). "In contrast to the promoting effect of GLI2A overexpression on glioma xenograft growth, both GLI2 inhibition and ARHGEF16 knockdown retarded tumor growth." (PMID 30305138, 2018). "To identify novel target genes of GLI transcription factors, we overexpressed GLI2A-a constitutively active form of GLI2-by LV infection in GLI2A U87 glioma cells and compared the gene expression profiles with that of U87 Control cells by microarray analysis." (PMID 30305138, 2018). "Our finding that ARHGEF16 is a target of GLI2 provides the first evidence of potential cross-talk between the Hh and Ephrin signaling pathways in glioma development." (PMID 30305138, 2018). "MiR-326 down-regulated the external secretion of TGF-β1 via the SMO/Gli2 pathway instead of by targeting the 3′-UTR of TGF-β1 in the glioma cells, and this resulted in a reversal of the glioblastoma-associated immunosuppressive environment." (PMID 28412740, 2017). "We found that GDC-0449 treatment significantly decreased the expression levels of Gli1 and Gli2 in glioma cells." (PMID 28195165, 2017). "On the other hand SHH, SMO, GLI1, GLI2, GLI3_A (core Hedgehog pathway molecules) were activating the other proteins in both normal as well as Glioma scenarios." (PMID 23935937, 2013).
glioma (continued). "We found that compared to GLI1, GLI2 was more potential activator of Glioma scenario as it was connected with GLI1 which was also an important activator in the network." (PMID 23935937, 2013). "Gli1, the founding member, was initially identified as being highly amplified in gliomas, and Gli2 and Gli3 were subsequently cloned by hybridization." (PMID 20865152, 2010). "Gli1 and Gli2 control the expression of Bmi‐1 by their binding to the Bmi‐1 promoter and eventually upregulating multidrug‐resistant proteins that promote chemoresistance in glioma cells." (PMID 39791545, 2025). "In addition, the GLI1 expression levels were particularly high in grade III and IV gliomas, whereas GLI2 was found overexpressed only in grade III tumors." (PMID 35409080, 2022). "Existing research demonstrated that Gli2/miR-124/AURKA axis might be the key to influencing AURKA’s effect on glioma." (PMID 35201446, 2021). "It has been verified that circRNAs and their host genes could be regulated by the common transcription factor and Gli2 was previously verified to transcriptionally activate ARHGEF16 in glioma cells." (PMID 32493490, 2020). "Thus, CKAP5 acts in conjunction with ARHGEF16 to promote glioma cell migration and proliferation induced by GLI2." (PMID 30305138, 2018). "Furthermore, the effects of GLI2 inhibition on glioma growth were supported by the lower protein levels of ARHGEF16 as well as Ki67 and MMP9 in GLI2A, GANT61 group than in GLI2A, vehicle group, as determined by immunohistochemistry." (PMID 30305138, 2018). "Moreover, cell migration and proliferation were enhanced in GLI2A + sh-Control U87 cells relative to Control+sh-Control U87 cells, suggesting that GLI2 promotes glioma cell migration and proliferation through ARHGEF16." (PMID 30305138, 2018). "In this study we identified ARHGEF16 as a target gene of GLI2 in glioma cells." (PMID 30305138, 2018). "We find that increasing ARL13B in glioma cilia stimulates ciliary elongation and an increase in SMO/GLI2 accumulation." (PMID 37830570, 2023). "We first examined the relationship of ARL13B expression and another key ciliogenesis gene, IFT88, with the expression of other SHH pathway genes (SMO, GLI2, and SHH) in low-grade glioma (LGG) and high-grade glioblastoma (GBM) using TCGA datasets." (PMID 37830570, 2023). "Gliomas with increased ARL13B, SMO, and GLI2 expression are more aggressive, but the relationship to cilia is unclear." (PMID 37830570, 2023). "The Gli2/miR-124/AURKA occupies an essential position during the growth and development of human glioma cells." (PMID 35201446, 2021). "The incubation of glioma cells with siRNA against GLI1, GLI2, or GLI3 resulted in death of glioma cells." (PMID 30730955, 2019). "According to our data, treatment of glioma cells with GANT61 or siRNA against GLI1, GLI2, or GLI3 resulted in their death, indicating, that gli contribute to glioma cells survival." (PMID 30730955, 2019). "The expression of GLI1, GLI2, GLI3 and their target genes FOXM1 and BMI1 was analyzed by RT-qPCR for 20 glioma cell lines and a normal adult brain tissue." (PMID 30730955, 2019). "The treatment of glioma cells with cyclopamine, GANT61 or siRNA against GLI1, GLI2, or GLI3 significantly decreased the expression of GLI1, FOXM1, BMI1, SOX2, and OCT4, involving in the maintenance of the stem cell state." (PMID 30730955, 2019). "High levels of Gli2 suppress the miR-124 level, leading to increased levels of AURKA in glioma cells." (PMID 29899399, 2018). "Apart from SHH, experimental evidence also showed that ERK12, TWIST and RAS proteins were up regulated during Glioma and these were known to have a direct effect on the abnormal activation of GLI1 and GLI2." (PMID 23935937, 2013). "Since the 1987 discovery of GLI1 in human glioma cells, the role of the three members GLI1, GLI2 and GLI3 in a variety of cancers has become increasingly apparent, with GLI1 expression specifically identified as a negative prognostic factor in numerous cancers." (PMID 34639011, 2021).
glioma (continued). "Thus, the expression of the components of the Shh signaling pathway, including GLI1, GLI2, GLI3, PTCH, and SMO, was found to be common in various tumors of the nervous system, including gliomas, and correlated with a poor prognosis of patient survival." (PMID 30730955, 2019). "Treatment with GANT61 or siRNA against GLI1, GLI2, or GLI3 could result in complete glioma cell death, while cyclopamine had a weaker and line-specific effect on glioma cell survival." (PMID 30730955, 2019). "From our study we observed the under expressions of various oncoproteins in Hedgehog pathway while perturbing at a time the combinations of the proteins GLI1, GLI2 and SMO in Glioma; SMO, HFU, ULK3 and RAS in Colon cancer; SMO, HFU, ULK3, RAS and ERK12 in Pancreatic cancer." (PMID 23935937, 2013). "In case of Glioma, the total numbers of activators on GLI1 and GLI2 proteins were 16 and 6, whereas in case of normal scenario there were 11 and 5 proteins activating the expression of GLI1 and GLI2 proteins, respectively." (PMID 23935937, 2013). "Therefore, in order to suppress the GLI activation in cytoplasm, we directly blocked the activity of GLI1 and GLI2 in cytoplasm and also SMO in membrane of the Glioma scenario (GS) by putting ‘0’ or “OFF” as their logical states." (PMID 23935937, 2013). "Our results indicate that the GLI2/ARHGEF16/CKAP5 axis promotes glioma progression by enhancing tumor cell migration and proliferation and could therefore serve as a therapeutic target for glioma treatment." (PMID 30305138, 2018). "The relationship between ARL13B, SMO, and GLI2 may be independent of SHH expression in glioma." (PMID 37830570, 2023). "Moreover, we identify GRNs (for example, GLI2 and NFATC4) that have not yet been implicated in normal development and may hence present glioma-specific regulatory aberrations." (PMID 36471067, 2022). "However, glioma cell lines whose cilia overexpress WT but not guanine exchange factor-deficient ARL13B, display reduced INPP5e, a ciliary membrane component whose depletion may favor SMO/GLI2 enrichment." (PMID 37830570, 2023).